STAT3 (signal transducer and activator of transcription 3)
Diseases named in the same sentence as STAT3 in open-access papers (continued):
Sharing a sentence is not in itself a finding about the gene and the disease.
tumor (continued). "In this last context, it is interesting that both in vivo and in vitro studies indicate that IL-6 produced by stromal tumor associated fibroblasts also enhances OC cell proliferation through activated signal transducer and activator of transcription 3 (STAT3) signaling." (PMID 21765834, 2011). "STAT3 target genes are implicated in multiple steps of tumour metastasis including cell invasion, survival, renewal and angiogenesis and thus pSTAT3 can be regarded as a pivotal regulator of tumour metastasis." (PMID 20553623, 2010). "Although STAT3 activation induces recruitment of hematopoietic cells, STAT3 activation in tumor-associated macrophages (TAMs) and DCs has a profound anti-inflammatory effect by preventing their maturation and blocking their ability to produce many proinflammatory cytokines such as IL-12." (PMID 20885915, 2010). "Stat3 may therefore increase the pool of "stem" cells susceptible to tumour-inducing mutation, including loss-of-heterozygosity in ApcMin mice." (PMID 20478049, 2010). "Conversely, excessive Stat3 activation, through epithelial-specific Socs3 ablation or introduction of the Socs3-binding deficient gp130Y757F mutation, results in increased tumour burden both in terms of tumour size as well as incidence." (PMID 20478049, 2010). "Importantly, IL-6 promotes tumor progression in inflammation-associated tumor models through the activation of STAT3." (PMID 20885960, 2010). "Specifically as MMP-2 serves to degrade ECM and basement membranes underlying tumor cell invasion and migration, we showed by using an invasion assay in vitro that STAT3 downregulated tumor cell lines exhibit significant decreased invasion capability when compared with control." (PMID 24281074, 2010). "In response to tumour-derived IL10 and VEGF, for instance, excessive Stat3 activity in myeloid cells inhibits maturation and activation within the DC lineage, favours polarization and activation of tumour associated macrophages (TAM), and reduces cytotoxic activity of neutrophils and NK cells." (PMID 20478049, 2010). "Furthermore, recent studies demonstrated that SFK inhibition in various carcinoma tumor cell lines resulted in loss of STAT3 activity." (PMID 19284568, 2009). "The tight association of STAT3 activation with transformation and tumour progression makes it an attractive molecular target for novel cancer therapeutics development and many substances have been tested for their effect on STAT3." (PMID 19455144, 2009). "Some characteristics of tumor biology, like deregulated expression of gangliosides and constitutive activation of signal transducer and activator of transcription (STAT)-3, have been implicated in tumor-host interactions, i.e. tumor immune escape and angiogenesis." (PMID 19519895, 2009). "Therefore, the inhibition of tumor growth by STAT3 decoy ODN was significantly associated with blockade of the STAT3-regulated cell cycle and anti-apoptotic proteins." (PMID 17683579, 2007). "Moreover, cellular components such as cancer-associated fibroblasts (CAFs), tumor-associated macrophages (TAMs), and regulatory T cells (Tregs) drive immune evasion and therapeutic resistance via cytokine signaling axes, including IL-6/STAT3 and CXCL12/CXCR4." (PMID 42294061, 2026). "RES demonstrates similar effects by suppressing STAT3 signaling, resulting in a 30%–50% reduction in tumor growth and a marked decrease in the M2 polarization of tumor‐associated macrophages, thereby disrupting the communication between cancer cells and the tumor microenvironment." (PMID 40860906, 2025). "Interestingly, interleukin-6 (IL-6)/STAT3 signaling has also been implicated in EMT within tumor-infiltrating myeloid cells (TIMs), CAFs, and tumor-associated adipocytes, suggesting that STAT3/IL-6 pathways may jointly participate in GPR81-mediated EMT." (PMID 40948941, 2025).
tumor (continued). "Moreover, STAT3 downregulation led to a loss of tumor-forming ability in immunodeficient mice." (PMID 40177538, 2025). "While STAT3 constitutive activation has been linked to the development of several solid cancers, including NB, recent research has also suggested that this TF may function as a tumor suppressor in specific contexts and conditions." (PMID 39843641, 2025). "Furthermore, the overactivation of STAT3 is often associated with inflammatory responses in the tumor microenvironment, and FN1 may also participate in these inflammatory responses during extracellular matrix remodeling." (PMID 40772037, 2025). "Furthermore, in the two-group comparison of clinical factors and n-STAT3 scores, significant differences were observed in clinical factors such as tumor size, clinical N1b status, and number of LNMs, indicating an association with high-risk factors for recurrence in the low n-STAT3 group." (PMID 41104968, 2025). "Additionally, phosphorylated STAT3 in cancer-associated fibroblasts (CAFs) drives angiogenesis and tumor growth, and phospho-STAT6 supports M2 macrophage polarization through JAK1 signaling, emphasizing the immunoregulatory impact of phosphorylation in the tumor microenvironment." (PMID 41359051, 2025). "We examined 21 biopsy samples gene expression of glioblastoma patients, which showed elevated expression of G-CSF, G-CSFR, and STAT3 at the transcriptome and proteomic levels compared to tumor-associated normal tissue (TANT), which might be considered diagnostic and prognostic biomarkers." (PMID 38538691, 2024). "One theory is that stromal cells or tumor-associated macrophages (TAMs) could protect tumor cells from drug-induced apoptosis via secreting interleukin-6 (IL-6) to activate signal transducer and activator of transcription 3 (STAT3) pathway of tumor cells." (PMID 38238749, 2024). "Similarly, STAT3 activation is associated with tumor angiogenesis and metastasis." (PMID 38612893, 2024). "Moreover, STAT3 activation in tumor-associated immune cells leads to anti-tumor immune suppression." (PMID 38683372, 2024). "STAT3 is persistently activated in a wide diversity of cancers and is positively associated with cell proliferation, cell survival, invasion, and metastasis, although tumor suppressor activities under certain conditions, and in certain cancers, have also been reported for STAT3." (PMID 39041323, 2024). "Moreover, IL6 from tumor-associated macrophages (TAMs) activates the JAK/STAT3 pathway, leading to transcriptional inhibition of tumor suppressors, while caspase-related IL-8 is considerably related to the recruitment of anti-inflammation macrophage through neutrophil." (PMID 38844562, 2024). "IL-6/STAT3 tumor stemness may be associated with elevated reactive oxygen species (ROS) levels." (PMID 39092186, 2024). "Also, epigenetic modifications and mutations could alter the balance between pro-oncogenic and tumor suppressor activities of the STAT3/5 signaling pathway." (PMID 39136000, 2024). "Indeed, the inhibition of STAT3 following LDHC silencing restored the loss-of-tumor cell survival." (PMID 39001513, 2024). "However, our group has recently challenged active IL-6/STAT3 signaling as a tumor driver in PCa, as loss of Stat3 unexpectedly resulted in increased tumor burden and was accompanied by a bypass of PTEN-loss induced cellular senescence (PICS) in a Pten-deficient PCa mouse model." (PMID 38811984, 2024). "Moreover, in terms of SNPs distant effect, trans‐eQTL results indicated that STAT3 expression was positively associated with Foxp3 expression in both tumor (statistics r: 0.794, β‐Score: 1.109) and higher infiltration groups (statistics r: 0.411, β‐Score: 0.484)." (PMID 36226375, 2023).
tumor (continued). "Furthermore, STAT3 pathway activation in different immune cell subtypes is associated with the production of immunosuppressive factors, which can induce myeloid-derived suppressor cells, which serve a major role in tumour promotion and progression." (PMID 36825563, 2023). "In the arena of drug-resistant neoplasms, scholarly research suggests that Leo can depress the expression of resistance-associated proteins present in drug-resistant lung adenocarcinoma cells and inhibit cellular proliferation by stifling STAT3 activation, thus combating drug resistance." (PMID 37818195, 2023). "Converse to our hypotheses, Kaplan–Meier survival analysis showed low tumour nuclear (surrogate marker of activation) expression of STAT3 was significantly associated with reduced outcome in the full cohort (HR = 0.671, 95% CI: 0.469–0.961, log rank p = 0.029)." (PMID 37199043, 2023). "TAMs can be recruited into the tumor microenvironment after the colonization of tumor cells in metastatic organs to form an immune microenvironment and act as mediators of cancer-associated inflammation through the release of transcription factors (NF-κB, STAT3) that promote tumor growth." (PMID 36910657, 2023). "STAT3 is reported to be a master regulator of cancer hallmarks and it is wildly associated with cell proliferation, resistance to apoptosis, metastasis, immune evasion, tumor angiogenesis, epithelial mesenchymal transition (EMT), chemo-resistance, response to DNA damage, and the Warburg effect." (PMID 38304256, 2023). "Thus, our data demonstrate that Q11 can improve the tumor microenvironment by attenuating oxidative damage and inhibiting the inflammatory response, which may be associated with the IL‐6/STAT3 pathway and the MAPK/ERK pathway." (PMID 37875398, 2023). "In addition, intracellular STAT3 activation in immune cells causes suppressive effects on antitumor immunity and leads to the differentiation and mobilization of immature myeloid-derived cells and tumor-associated macrophages." (PMID 36010693, 2022). "On the other hand, the mutation-driven excessive STAT3 activity in NK cells from patients with chronic lymphoproliferative disorders of NK cells, T-cell large granular lymphocytic leukemias, and NK/T-cell lymphomas of the nasal type promotes lymphomagenesis and provides a tumor-promoting TME." (PMID 36010693, 2022). "Importantly, in the mouse model of liver carcinogenesis, TGR5 knockout mice had a higher incidence of hepatocellular carcinoma than WT mice, and Stat3 phosphorylation, which is substantially associated with an increased tumor progression, was 2-fold higher than in WT mice liver." (PMID 35889921, 2022). "Therefore, active STAT3 signaling in the tumor cells, evident by nuclear localization of STAT3, was associated with infiltrating FOXP3-T-cell numbers, suggesting that nuclear STAT3 may be associated with increased active immune response." (PMID 35267462, 2022). "Furthermore, the researcher discovered that paeoniflorin could inhibit the phosphorylation of both JAK and STAT3 pathways, which were associated with the expression of PD-L1 in tumor cells." (PMID 36615387, 2022). "In addition to being a core early event in OSCC, abnormal STAT3 activation represents a potential risk factor for poor prognosis in early-stage patients and in later disease stages correlates with poor tumor differentiation, lymph node metastasis and reduced survival." (PMID 35844493, 2022). "To address this question, we determine whether the acquisition of spheroid-forming ability in HCC, which is associated with the existence of human CSCs and tumor-initiating cells (TICs), correlated with activation of STAT3 by TrkC-mediated inhibition of DJ-1 degradation." (PMID 36202793, 2022).
tumor (continued). "IL-6 levels were elevated both in the tumors and serum of tumor-bearing mice which was also associated with increased protein concentrations of the IL-6 regulated transcription factor pSTAT3 and increased expression of downstream targets of IL-6 signaling in the liver (e.g., Stat3)." (PMID 35663547, 2022). "Besides T cells, S1PR1 was also involved in STAT3 activation in tumor-associated myeloid cells." (PMID 35163211, 2022). "In addition, JAK/STAT3 is also associated with tumor metastasis and blood vessel formation." (PMID 35559037, 2022). "Importantly, aberrant STAT3 activation is associated with tumor promotion and progression of CCA." (PMID 34837926, 2021). "However, when unchecked STAT3 can exploit the wound healing characteristics of cancer-associated fibroblasts (CAFs) to sculpt a tumor milieu that is conducive to fibrosis, cancer cell migration and dissemination, while limiting immune cell-infiltration and responsiveness to therapy." (PMID 34858425, 2021). "In tumor cells and tumor microenvironment, excessive cytokines and functional mutation of kinase pathway members alter the regulation of tyrosine kinase pathway, providing a hyper-phosphorylation status at STAT3- Tyr705, which drives the head-to-tail dimerization and following activation." (PMID 34502195, 2021). "Because of that, the tumor immune infiltration of T cell is closely associated with the efficiency of the immune checkpoint inhibitor therapy; thus, we evaluated the impact of the expression of STAT3/CDK2/4/6 on the therapeutic outcome of immune checkpoint blockade." (PMID 33668805, 2021). "Indeed, TA-mediated suppression of tumor cell viability is associated with multiple biochemical actions, including inhibition of protein synthesis, reduced activating phosphorylation of STAT3 and S6K1, decreased expression of the MYC oncoprotein, and suppression of Lys acetylation." (PMID 35095503, 2021). "In addition, miR-1246 in tumor EVs activated STAT3 and Akt, causing drug resistance in ECs." (PMID 34226586, 2021). "It is tempting to speculate that STAT3 activation is involved in DNM2 upregulation in cancers and that DNM2 overexpression may be an effector of features associated with abnormal STAT3 activation in cancers such as tumor growth and metastasis leading to poor prognosis." (PMID 34294140, 2021). "The STAT-3 signaling pathway was also found to play a key role in meditating the effect of IL-6 on promoting tumor progression and treatment resistance by inhibiting cancer cell apoptosis and stimulating tumor-associated factors among various signaling pathways." (PMID 33582655, 2021). "Therefore, we sought to assess whether tumor-associated NLRP3 activity also affects the IL-1β/IL-6/STAT3 axis in host myeloid cells." (PMID 34531850, 2021). "Additionally, cytokines and growth factors produced by tumor-associated immune cells and fibroblasts activate STAT3 in tumor cells, forming a feed-forward loop to maintain activated STAT3 in both transformed and untransformed cells in the tumor microenvironment." (PMID 33491667, 2021). "STAT3 is a transcriptional factor that is primarily activated by IL-6 family cytokine receptor-associated Janus kinases (JAKs) and had a prominent role in regulating the proliferation, survival, invasion, and metastasis of tumor cells as well as immunosuppression." (PMID 34922636, 2021). "Indeed, a number of chemotherapeutic drugs as well as Shp1-targeting natural compounds induce Shp1-mediated dephosphorylation of p-STAT3Tyr705; this downregulates STAT3 transcriptional activity causing a block of tumor cell proliferation and induction of apoptosis." (PMID 32596156, 2020). "Thus, STAT3 activation in immune cells is associated with suppression of anti-tumor immunity." (PMID 32150944, 2020).
tumor (continued). "Importantly, reduced caloric intake and regular exercise have been shown to reduce the serum concentrations of IL-6, TNFα and are associated with reduced activity of tumor-promoting transcription factors, including activator protein (AP)-1, STAT3 and NF-kB in various tissues." (PMID 32825010, 2020). "Therefore, researchers detected the expression of STAT3 phosphorylation and Snail in tumor cells interacted with TAMs and tumor-associated endothelial cells expressing or overexpressing B-cell lymphoma-2 (Bcl-2), which could promote the secretion of IL-6." (PMID 32161718, 2020). "Furthermore, CTLA4apt-STAT3 siRNA can dramatically reduce tumor-associated Tregs." (PMID 33123281, 2020). "Thus, the PHB ligand FL3 inhibited induction of HIF1α and reduced STAT3 transcriptional activity suggesting that the growth inhibition by FL3 may be caused by inhibition of pro-tumorigenic STAT3 signaling in tumor cells." (PMID 33257655, 2020). "Therefore, while we are just beginning to understand effective means of targeting STAT3, this may present a novel means for inhibiting cancer cell plasticity and associated tumor progression." (PMID 32391382, 2020). "In addition to promoting cell survival and proliferation, constitutive activation of STAT3 in cancer cells causes high levels of PD-L1 expression, which may facilitate tumor immune evasion." (PMID 31861597, 2019). "Therefore, niclosamide, also as a STAT3 inhibitor, may have dual anti-cancer effects on both tumor cells and the tumor-associated immune environment." (PMID 31511071, 2019). "Further studies should be undertaken to examine the possible synergetic effects on tumor suppression, the tumor microenvironment, and associated biological mechanisms that could be provided by blocking STAT3 with STX-0119 in combination with the other chemotherapeutics." (PMID 32257917, 2019). "The observed hyperactivation of STAT3 in antigen-presenting cells (APCs) has been associated to T cell tolerance in GB and has been implicated to the expansion T-helper cells expressing IL-17 which blocks Th1 anti-tumor response and accelerates its progression." (PMID 31698775, 2019). "Moreover, malajusted miR- 155-5p/C/EBPβ/IL6 signaling in tumor-associated macrophage could induce chemoresistance by regulating the IL6R/STAT3/miR-204-5p axis." (PMID 30897064, 2019). "Cancer mutations and epigenetic alterations may alter the balance between pro-oncogenic and tumor suppressor activities associated with STAT3/5 signaling, explaining their context-dependent association with tumor progression both in human cancers and animal models." (PMID 31557897, 2019). "However, an increasing body of evidence supports the idea that STAT3 could have pro-tumorigenic or anti-tumorigenic activities depending on the specific tumor type, mutational landscape, stage of carcinogenesis, and metabolic conditions." (PMID 31551419, 2019). "Consequently, Stat3-deficiency in IEC reduced tumor growth in Stat6−/− mice." (PMID 30353167, 2019). "Thus, in the inflammatory areas, inflammatory cytokines downregulated PDCD4-protein levels in surrounding cells via NF-κB-miR21 and/or STAT3-miR21 axis and by the degradation of the protein resulting in high-risk environmental conditions for tumor promotion and carcinogenesis." (PMID 31075975, 2019). "Therefore, the attenuation of mTOR signaling in the skeletal muscle of tumor-bearing mice might be caused by the activation of STAT3 signaling through the enhanced production of adipocyte IL-6." (PMID 30555329, 2018). "A possible explanation is that p-STAT3-positive patients may be associated with better response to neoadjuvant and adjuvant chemotherapy because activated p-STAT3 could contribute to microtubule formation and promote tumor cell dissemination." (PMID 29560131, 2018).